IDO1 (indoleamine 2,3-dioxygenase 1)
Diseases named in the same sentence as IDO1 in open-access papers (continued):
Sharing a sentence is not in itself a finding about the gene and the disease.
tumor (continued). "Taken together, Roxyl-WL represents a novel IDO1 inhibitor against diseases characterized by immune suppression and is a immunotherapeutic agent, which may help to resist the immune tolerance of the tumor microenvironment." (PMID 29932010, 2018). "This phenomenon could be partially explained by the greater inflammatory potential of these animals when compared to WT mice, since IDO1−/− tumor-bearing mice showed higher frequencies of resident monocytes in spleens and inflammatory monocytes in both spleens and blood." (PMID 30186285, 2018). "Indeed, several pathological parameters, such as tumor size, lymph node metastasis and advanced disease stage, emphasize the role of IDO1 expression in promotion of tumor growth and highlight the potential positive impacts of IDO1 inhibition in the fate of tumor treatments." (PMID 30186285, 2018). "Moreover, molecule 20a exhibited high potent in vivo antitumor efficacy (tumor growth inhibition (TGI) = 58.2%) compared with clinical candidate IDO1 inhibitor epacadostat (TGI = 47.5%) in the allograft animal model with CT-26 without remarkable body weight loss or adverse effects." (PMID 30618747, 2018). "However, we do not object their opinions, we believe that IDO1 may derive from normal cells, or it is possible that IDO1 is one of the tumor's autocrine hormones." (PMID 28903363, 2017). "From this initial PET imaging study, there were not significantly uptake of [11C]-AMT and [18F]IDO49 in lymph nodes of HeLa tumor bearing models, which display positive IDO1 expression in IHC, it may need a longer PET acquisition time to obtain an accurate imaging in lymph nodes." (PMID 28159919, 2017). "Moreover, the findings also propose that IDO1 might potentially play alternative functions that regulate myeloid cells (e.g., neutrophils or MDSCs) in other contexts, such as tumor context." (PMID 28191010, 2017). "Thus, the mutation frequency of APC in the present study fell within the range reported in Asian populations but was lower than that in European or US populations, pointing to the potential role of an IDO1-regulated molecular pathway in tumor formation in Asian populations." (PMID 27578919, 2016). "How IDO1 expression in human tumor cells is regulated by tumor milieus remain unclear." (PMID 26895379, 2016). "We then ask whether PBMC were necessary for the maintenance of IDO1 expression in tumor cells." (PMID 26895379, 2016). "Tryptophan metabolism mediated by IDO1 generates biologically active kynurenine pathway metabolites, leading to differentiation and/or activation of FoxP3-expressing regulatory T cells (Treg), to suppression of anti-tumour T-cell responses and to reduced dendritic cell (DC) immunogenicity." (PMID 23973990, 2013). "Therefore, despite the apparent increase in CTL and NK cells in hiEBVaGCs, the activated IFNG signaling may counteract this response through IDO1 mediated Trp depletion; allowing tumor survival." (PMID 23671415, 2013). "Thus, a role for IDO1 in tumor immune response is indicated but requires further investigation." (PMID 22654951, 2012). "In contrast to our expectation, growth of the Ido1− tumors was slower than growth of Ido1+ tumors in immunodeficient SCID/beige mice, suggesting that some Ido1-associated nonimmunological mechanisms may be involved in tumor cell growth regulation." (PMID 22654951, 2012). "Our study reveals that in NSCLC cells, upregulated PRMT3 promotes IDO1 expression by methylating TFAP2A, thereby activating the tumor’s intrinsic Kyn metabolism and mediating the development of radiation resistance." (PMID 41129671, 2026). "The high expression of indoleamine 2,3-dioxygenase 1 (IDO1) in tumors facilitates the conversion of tryptophan to kynurenine, thereby promoting the establishment of a tumor immune-suppressive microenvironment." (PMID 41424843, 2026).
tumor (continued). "In tumor cells, PRMT3 mediated arginine methylation of transcription factor TFAP2A, enhancing its binding to the indoleamine 2,3-dioxygenase 1 (IDO1) promoter." (PMID 41129671, 2026). "As a highly selective IDO1 inhibitor, NLG919 has demonstrated potential in reversing tumor immune evasion." (PMID 41424843, 2026). "Diaryl hydroxylamines have emerged as promising scaffolds for targeting the tryptophan-catabolizing enzymes indoleamine 2,3-dioxygenase 1 (IDO1) and tryptophan 2,3-dioxygenase (TDO), key drivers of tumor immune escape." (PMID 41945792, 2026). "The dual inhibitor RY103, which targets both IDO1/TDO2 and the KYN-AHR-AQP4 axis, has been shown to suppress tumor invasion and migration in GBM models." (PMID 41602107, 2026). "The enzyme Indoleamine 2,3‐dioxygenase 1 (IDO1) is regulated by the interferon‐driven STAT1 axis and contributes to the balance of the tumor microenvironment (TME)." (PMID 40062505, 2025). "Within the TME, IFN-γ induces excessive activation of IDO1 and TDO in both melanoma cells and tumor-infiltrating lymphocytes, leading to tryptophan depletion, thereby enhancing immune recognition." (PMID 40539068, 2025). "IDO1 promotes IL-6, which enhances MDSC generation and migration into tumor tissues, creating an immunosuppressive microenvironment." (PMID 41035912, 2025). "Existing literature suggests that IDO1 promotes EMT in BC through the IL-6/STAT3/PD-L1 signaling pathway, enhancing the migratory and invasive potential of tumor cells." (PMID 40287406, 2025). "IDO1 and TDO2, essential enzymes in the Kyn metabolic pathway, are commonly overexpressed in numerous tumor types, including those affecting the pancreas, breast, and brain." (PMID 41332472, 2025). "IL-15 enhanced the activation of T cells and natural killer cells, while IDO1 inhibitor suppressed Tregs, effectively restoring the IME in LNs and demonstrating potent anti-tumor activity." (PMID 40159756, 2025). "Liu's study revealed that in tumor‐repopulating cells (TRCs), IFN‐γ‐induced IDO1 promotes p27 transcription and expression via the kyn/AhR pathway." (PMID 40103267, 2025). "Moreover, researchers have demonstrated that RT caused significant reductions in IDO-1 activity during therapy, but increased significantly post-RT, suggesting that IDO-1 activity may be suppressed by anti-tumor immunity in some patients as early as 2 weeks after starting RT." (PMID 40475772, 2025). "Since IDO1 is crucial for kynurenine metabolism in tumor cells, how GPX4 regulates IDO1 levels via ROS was first investigated." (PMID 40365295, 2025). "This iBINP platform, developed by dual prodrug engineering and subsequent nanoparticle assembly, enabled tumor-restricted STING activation and IDO1 inhibition, achieving immune activation while mitigating immune tolerance." (PMID 41129257, 2025). "In melanoma, IDO1 was found to stimulate the SHP-2/RAS/ERK signaling axis, thus contributing to tumor growth." (PMID 40137109, 2025). "In contrast, the tumor areas commonly expressed high CTLA4, low PD‐L1 and CD274, and very low IDO1 in sample HCC3." (PMID 41057994, 2025). "By suppressing both IDO1 and TDO2, DN1406131 13 attempts to prevent tryptophan depletion and kynurenine buildup within the tumor microenvironment, reactivating anti-tumor immunity." (PMID 41035912, 2025). "Tumor immune checkpoints (TICs) such as PDCD1 (PD-1), CTLA4, IDO1, and CD40 are critical regulators of immune responses and have emerged as promising therapeutic targets in cancer immunotherapy." (PMID 40918116, 2025). "M4112, as an effective and selective dual inhibitor of IDO1 and TDO2, was shown in a tumor mouse model to possess dual inhibitory effects." (PMID 39940736, 2025). "Tryptophan is degraded to kynurenine by indoleamine 2,3-dioxygenase 1 (IDO1), which is present in the tumor microenvironment (tumor, stromal and immune cells)." (PMID 39941796, 2025).
tumor (continued). "To further evaluate the localization relationship between IDO1 and GPX4, we performed IF staining for IDO1/GPX4 in xenograft mice tumor tissues." (PMID 41438182, 2025). "Smith's study discovered that silencing IDO1 in a KRAS‐induced lung adenocarcinoma model reduced the number of blood vessels in both tumors and non‐tumor tissues." (PMID 40103267, 2025). "The study examines the use of next-generation checkpoints like LAG-3, TIM-3, TIGIT, IDO1, and VISTA to overcome resistance to CTLA-4/PD-1 inhibitors, particularly in GBM, where the immunosuppressive tumor microenvironment presents significant challenges." (PMID 40514725, 2025). "Our aim is to investigate the KP with a broadened scope, exploring the IDO1, IDO2, TDO2 and AhR interplay with both clinical as well as tumour characteristics." (PMID 40471422, 2025). "In contrast, when Ido1 was knocked out from the tumor cells (4T1Ido1-KO), the activity of STING-NP monotherapy was recovered, showing similar tumor growth inhibition to iBINP treatment." (PMID 41129257, 2025). "To explore the metabolic and immune statuses within the TME, we used mIF to detect the expression of IDO1, KYN, and CD8 in the tumor tissues of each group." (PMID 39661740, 2025). "The intelligent HMP1G NPs respond to H+ and glutathione in the tumor microenvironment (TME), They downregulate tumor‐derived IDO1 via the AhR/STAT3/IL axis, improve the KYN/TRP metabolic imbalance, and effectively counter immunosuppression in the TME." (PMID 39661740, 2025). "LAMP3+ DCs are involved in tryptophan metabolism via IDO1 and can also promote pro‐angiogenic signaling through the VEGFA–NRP2 axis, contributing to tumor progression." (PMID 40667699, 2025). "The whole-cell proteomics detected 157 differentially expressed proteins, including upregulated IDO1 and legumain (LGMN) in tumor-induced DC3s." (PMID 40789452, 2025). "As IDO-1 introduces tumoral immune resistance, IDO-1 inhibitors exert anti-tumor immunity by activating the CD8+ cytotoxic T cell and inhibiting the differentiation of suppressor cells such as regulatory T cells." (PMID 40806744, 2025). "Indoleamine 2,3-dioxygenase 1 (IDO-1) and interferon-gamma (IFN-γ) are proteins that play a significant role in inflammatory conditions and tumor development." (PMID 40710094, 2025). "Collectively, these results suggest that IDO1 is upregulated upon the MSA-2–induced activation of the STING pathway, with this transcriptional activation likely to occur in both tumor and immune cells." (PMID 41129257, 2025). "The combination of IDO1 inhibitors and ICIs significantly suppresses IDO1 overexpression and stimulates the proliferation of effector CD8+ T cells, thereby augmenting the efficacy of anti-tumor immunotherapy." (PMID 40708940, 2025). "Inhibiting IDO1 expression enhances CD8+ T‐cell infiltration, reactivates antitumor immunity, and delays tumor growth." (PMID 41332472, 2025). "Exhaustion markers including PDCD1, IDO1, and HAVCR2 were predominantly enriched in tumor-adjacent regions, which exhibited partial spatial overlap with ADM expression." (PMID 40547013, 2025). "COX‐2 acts in the tumor microenvironment (TME) through a variety of mechanisms, such as inhibiting tumor cell apoptosis, promoting prostaglandin E2 (PGE2) release, and inducing IDO1 production." (PMID 40452814, 2025). "Meanwhile, we aimed to delineate the causes of TME immunosuppression by collecting normal mouse mammary glands and tumor‐bearing mouse BRCA tissues for qualitative and quantitative analysis of IDO1." (PMID 39661740, 2025). "IDO-1 also induces tryptophan depletion and kynurenine accumulation in the TME, driving tumor resistance to ICIs." (PMID 41019983, 2025). "Next, CD3+CD8+ T cell, CD4+FOXP3+ TReg, PDL1Tumor, NOS2Tumor, COX2Tumor, IDO1, and B7H4 density heatmaps were spatially examined relative to stroma as well as viable and necrotic annotated tumor regions." (PMID 40663402, 2025).
tumor (continued). "TDO, IDO1, and IDO2, which catalyze the first and rate-limiting step of TRP degradation via the KP, leading to NFK generation, are involved in tumor development and immune modulation." (PMID 40332338, 2025). "This seminal paper systematically assessed the therapeutic potential of key enzymes—IDO1, IDO2, TDO, and KMO (Kynurenine 3-monooxygenase)—highlighting their roles in immune modulation and tumor immune evasion." (PMID 40666095, 2025). "Immune alterations also include increased CD4 +/CD8 + and IL-17 + γδ T cells, and elevated expression of immunosuppressive (IDO1, IL-10, PD-L1) and oncogenic (AKT1, STAT3, CXCR4) genes with key roles in tumor progression and immune evasion." (PMID 40924302, 2025). "Our aim was to explore the correlation between key KP markers; IDO1, IDO2, TDO2, its primary effector target aryl hydrocarbon receptor (AhR) and a comprehensive set of clinical- and tumour characteristics." (PMID 40471422, 2025). "Compound 2 exhibited potent IDO1 inhibition (IC50 = 5 nM) and demonstrated significant anti-tumor activity in vivo models of Lewis lung carcinoma (LL2) and hepatocellular carcinoma (Hepa1-6), with minimal toxicity." (PMID 41050410, 2025). "In KPIC orthotopic PC mice, inhibition of the IDO1/TDO2-Kyn-AhR pathway resulted in delayed tumor growth, suppressed tumor metastasis, and enhanced tumor cell apoptosis." (PMID 40136551, 2025). "This approach aims to enhance tumor immunogenicity in response to an acidic TME, inhibit IDO1 expression to ameliorate immune tolerance and reprogram the immunosuppressive metabolic environment to enhance antitumor efficacy." (PMID 39661740, 2025). "In colorectal cancer, aberrant Wnt5a signaling correlates with elevated IDO1 expression and reduced infiltration of cytotoxic CD8+ T cells, indicating a more immunosuppressive tumor microenvironment." (PMID 40917745, 2025). "Meanwhile, the level of immunosuppression factors in tumor tissues, such as LAG-3, CTLA-4, and IDO-1, increased significantly." (PMID 40487392, 2025). "IDO1 downregulates IFN-γ and upregulates IL-6, thereby promoting angiogenesis and facilitating tumor growth." (PMID 41035912, 2025). "For the analysis, the TMA cores were evaluated by an experienced head and neck pathologist and the mean expression of IDO1 and IL4I1 in the tumor was calculated and used for the subsequent analysis." (PMID 40332319, 2025). "The enzymes IDO1 and TDO2 are considered key therapeutic targets in the KYN pathway due to their role in immune suppression and tumor progression." (PMID 39997327, 2025). "IDO1 blockade has shown promise in suppressing CD8 T cell apoptosis in the TME of CRC and sensitizing tumor cells to radiation‐induced cell death." (PMID 40062505, 2025). "Xu's experiment revealed that SRF promotes EMT and increases tumor migration and invasion in OSCC cells by activating the IDO1 gene promoter and regulating the IDO1/Kyn‐AhR signaling pathway." (PMID 40103267, 2025). "Indoleamine 2,3-dioxygenase 1 (IDO1), which catabolizes tryptophan, is a potential target to unlock the immunosuppressive tumor microenvironment." (PMID 38632994, 2024). "Consistent with a functional role for IDO1 expression in driving IBD-CRC development, mice treated with 1-L-MT had a significantly lower tumour number and tumour burden compared to mice treated with vehicle." (PMID 39242821, 2024). "Immunohistochemistry and immunofluorescence analyses show that the expressions of IDO1 and CD34 in tumor tissues of RY103-treated mice were reduced." (PMID 39065567, 2024). "IDO1 is a tryptophan metabolizing enzyme and mediates the tryptophan depletion to escape cytotoxic T cell killing, as a core element in tumor-promoting inflammation, the IDO inhibitor therapy have confirmed that IDO1 reduces the role of tumor immune response." (PMID 38227591, 2024). "We observed colocalization of IDO1, PD-1, CD68 (marker of TAMs), and CD163 (marker of M2 macrophages) in the tumour stroma." (PMID 39351094, 2024).
tumor (continued). "Factors like severe hypoxia, tumor cell metabolites, inhibitory receptors, and molecules like TGFβ, PGE2, IDO1 contribute to NK cell dysfunction in HBV–HCC." (PMID 39000296, 2024). "In preclinical studies, the IDO1 inhibitor NLG919 in combination with Paclitaxel significantly reversed the M2-like TAMs phenotype and the immunosuppressive tumor microenvironment." (PMID 38185636, 2024). "Consistently, multicolor immunohistochemistry showed that the IDO1 inhibitor decreased the colocalization of CD31 with LC3 and TOMM20 in primary tumor tissues of the orthotopic OC mouse model." (PMID 38468343, 2024). "Expression of IDO1 is up-regulated by IFN-γ, which initiates a multi-signal response to neutralize pathogens and neoplasia." (PMID 38813870, 2024). "IDO1 and TDO are highly expressed in tumor cells, tumor stromal cells, dendritic cells, and macrophages in the tumor microenvironment, leading to the consumption of tryptophan and the accumulation of tryptophan-related metabolites." (PMID 38680483, 2024). "Inhibition of tumor- or immunosuppressive cell-expressed GLS1, ARG1, iNOS, IDO1, TDO and/or IL4I1 therefore constitutes a promising approach to alleviate tumor-induced immune suppression, either as monotherapy or in combination with other treatment modalities." (PMID 39211039, 2024). "Since IDO1 is expressed in normal pet rabbit mammary tissue, systemic administration of an inhibitor of the IDO1 pathway could potentially lead to local site effects, which could be avoided by selecting therapeutic modes that selectively target the tumor tissue, such as antibody drug conjugates." (PMID 39061522, 2024). "The oxaliplatin restored by the GSH greatly suppressed the tumor progression and induced immunogenicity, while the released NLG9219 overcame the immunosuppressive tumor microenvironment by deactivating the IDO‐1 activity." (PMID 40625908, 2024). "Therefore, focusing on the differential expression of IDO1 in different tumors and its prognosis in comparison with combination drug therapy, IDO1 could be a good immune checkpoint to start developing IDO1 inhibitor-related therapeutics to improve anti-tumor efficacy and patient survival." (PMID 38539263, 2024). "This pathway, driven by indoleamine 2,3-dioxygenase 1 (IDO1), facilitates immune evasion and promotes tumor progression by fostering an immunosuppressive environment." (PMID 39911818, 2024). "IDO1 is predominantly found in glial cells, neurons, microglia, DCs, monocytes, and macrophages, whereas IDO2 is primarily expressed in certain tumor cells." (PMID 39492834, 2024). "In a tumor model, ARID5A, an RNA-binding protein, acts as an mRNA stabilizer to promote IDO1 expression." (PMID 39438693, 2024). "Targeting IDO1 in conjunction with ICD-inducing chemotherapeutic agents represents a promising opportunity for enhancing both the initiation and sustenance of a tumor-specific T-cell immune response within the TME." (PMID 38591056, 2024). "Differential gene expression results revealed five genes (IDO1, IL6, TNF, CD209, and FOXP3) that were, on average, upregulated ≥ 2-fold or downregulated ≤ –2-fold in treated tumor regions relative to untreated tumor regions." (PMID 39335552, 2024). "In the tumor microenvironment, KYN produced by IDO1 and TDO2 induces an immunosuppressive effect through AhR activation, influencing the tumor microenvironment and impairing the immune system's ability to recognize and eliminate tumor cells." (PMID 38883986, 2024). "After treating tumors, analysis found that the tumor cells in the HCNSP+laser group were significantly apoptotic, accompanied by upregulation of IDO-1." (PMID 39128942, 2024). "At the study evaluation timepoint of 2 h post H-FIRE, we observed differential gene expression changes in the genes IDO1, IL6, TNF, CD209, and FOXP3 in treated tumor regions relative to paired untreated tumor regions." (PMID 39335552, 2024).